CD69 (CD69 molecule)
Diseases named in the same sentence as CD69 in open-access papers (continued):
Sharing a sentence is not in itself a finding about the gene and the disease.
breast carcinoma (21 papers, 2015 to 2026). "Concurrently, breast cancer samples with high spermidine metabolism showed a remarkable increase in the expressing levels of T-cell activation and effector-related gene CD69 in CD8+ T cells." (PMID 40959110, 2025). "Most importantly, a direct and highly significant correlation between CD69 levels and NK cell activity was demonstrated by Clausen’s team in a study involving 14 breast cancer patients tested repeatedly during chemotherapy." (PMID 37894222, 2023). "To test the physiological relevance of DC3-dependent induction of CD8+CD103+ T cells, we analyzed CD103 and CD69 expression in CD3+CD8+ T cells from 18 samples of primary luminal breast cancer." (PMID 32610077, 2020). "Further, CD69 antibody blockade reduces PD-1 and TIM3 expression in CD8+ T cells, which is associated with reduced lung metastasis in breast cancer." (PMID 32010142, 2019). "As observed in our study, there was an increase in the proportion of activated T cells (CD69+) in breast cancer." (PMID 30061900, 2018). "The same pattern was observed when we compared CD69 expression on Tregs and Tconvs isolated from tumors of the 4T1 breast carcinoma model." (PMID 26433463, 2015). "Notably, lymphocyte activation marker, particularly CD69 were upregulated in B, NK and T cells of breast cancer patients, pointing to an ongoing immune response in this context." (PMID 33538861, 2021). "In vivo, DC3s infiltrated luminal breast cancer primary tumors, and DC3 infiltration correlated positively with CD8+CD103+CD69+ tissue-resident memory T cells." (PMID 32610077, 2020). "The indirect culture of ASCsisolated from breast cancer patients and normal individuals with activated PBLs significantlyreduced NKG2D+ and CD69+ NK cells (P<0.05)." (PMID 28367424, 2017). "CD69 expression in lung and breast cancer tumors were positively correlated with immune checkpoint expression, T cell infiltration, and ImmunoPhenoScore (IPS), leading the authors to propose CD69 as predictive biomarkers for ICI treatment response." (PMID 40989699, 2025). "Similarly, when co-cultured with breast cancer cells, it was found that CD8+CD69+CD103+TRM exhibited higher levels of IFNG and tumor necrosis factor-alpha (TNF-α) compared to CD8+CD69+CD103−T cells, further mediating a more significant tumor-killing effect." (PMID 38553708, 2024).
HIV-1 infection (21 papers, 2009 to 2025). The type species of lentivirus and the etiologic agent of acquired immunodeficiency syndrome (AIDS). "CD69 is an early T-cell activation marker and a promotor of T-cell retention in tissues, with its expression being associated with T-cell activation in HIV-1 infection." (PMID 41227377, 2025). "HIV-1 infection was associated with significant reductions in the production of IFN-γ (P = 0.0264), expression of CD69 (P = 0.0110), and expression of NK cell inhibitory receptor Siglec7 (P = 0.0418)." (PMID 38364104, 2024). "Strikingly, blocking STAT5 activity in this way completely inhibited induction of the TRM phenotype by HIV-1 infection, preventing upregulation of CD69 and CXCR6." (PMID 35417711, 2022). "In this study, the levels of CD69 expression on CD8 T cells during acute/early HIV-1 infection were significantly higher in Bw4-homozygous individuals than in Bw6-homozygous individuals (P = 0.033)." (PMID 30147699, 2018). "We also evaluate the percentages of the early activation markers CD25 and CD69 in these cells at 36h post HIV-1 infection." (PMID 25875202, 2015). "First, we analyzed the expression of the early activation surface markers CD25 and CD69 in the activated cells at 36h after HIV-1 infection." (PMID 25875202, 2015). "The early activation marker CD69 on CD4+ T cells was also quantified because CD69+CD4+ T cells have been demonstrated as a major early target for HIV-1 infection." (PMID 24454812, 2014). "PHA-activated CD4+ T cells were used as a positive control, which displayed around 30% cells expressed CD69 expression and supported efficient HIV-1 infection in treated T cells." (PMID 22110688, 2011). "Both CD4+ and CD8+ T-cells expressing CD103/ItgαE and CD69 are affected during HIV-1 infection." (PMID 41227377, 2025). "Therefore, there appears to be a mechanism that overrides the requirement for the downregulation of CD69 for S1PR1 to be expressed in our models of HIV-1 infection of the human thymus as well as systemic infection." (PMID 37762169, 2023). "The finding that CD69-expression is substantially increased on the CCR7-CD56bright population supports a dominant role for immune activation in the observed alteration of this NK cell phenotype in chronic HIV-1 infection." (PMID 23028633, 2012). "Interestingly, while HIV-1 infection alone induced upregulation of CD69, additional exposure of these HIV-1-infected resting memory T cells to the homeostatic T cell cytokine interleukin-7 (IL-7) further boosted CD69 upregulation 4-fold, compared with HIV-1 or IL-7 alone." (PMID 35417711, 2022). "Alongside CD69, resting memory T cells also increased co-expression of the TRM marker CXCR6 during HIV-1 infection." (PMID 35417711, 2022). "We next examined the influence of HIV-1 infection on expression of CD4, CD69 and CD62L on resting CD4+ T cells." (PMID 25330112, 2014). "Therefore, the biological characteristics and functions of CD69 expression on TIGIT+NK cells in blood still need further investigation, especially in HIV-1 infection." (PMID 33717085, 2021). "Similar to HIV-1 infection, delivery and expression of Vpr by VLPs induced NFAT and resulted in T-cell activation measured by expression of the early T-cell activation marker CD69." (PMID 27383627, 2016). "We observed a decrease in the frequency of CD25+CD69+CD4+ T cells after HIV-1 infection when compared with non-infected cells." (PMID 25875202, 2015). "HIV-1 infection did not alter the expression of CD69 on the B cell subsets of young infected individuals." (PMID 25213015, 2014). "In order to understand whether phenotypic changes take place in B cell subsets with age in combination with HIV-1 infection, a panel of phenotypic markers including B cell inhibitory receptors PD1 and FcRL4 and activation molecules CD25 and CD69 was used." (PMID 25213015, 2014).
HIV-1 infection (continued). "In this study we examine the consequences of HIV-1 infection to naïve and memory resting CD4+ T cells, finding that CD62L was specifically down-modulated, the early activation marker CD69 was upregulated, and that these occurred concomitantly with HIV-1 suppression of Foxo1 activity." (PMID 25330112, 2014). "The expression levels of CD69, an early marker of CD4+ T cell activation, in WT HIV-1 infected cells were increased compared to mock-infected control cells at 3 dpi, indicating that HIV-1 infection activates resting CD4+ T cells." (PMID 22479639, 2012). "Although IL-7 can enhance HIV-1 infection of T cells, infection of resting memory T cells mediated by cell-to-cell spread does not require IL-7; furthermore, IL-7 increased CD69 expression on infected cells even when added 48 h post-infection." (PMID 35417711, 2022). "However, extensive analysis of T cell activation markers including CD25, CD69 and HLA-DR prior and during HIV-1 infection failed to reveal any correlation between the expression of these markers and detection of a Nef-dependent increase of HIV-1 replication (data not shown)." (PMID 19146681, 2009).
psoriasis (20 papers, 2019 to 2025). An autoimmune condition characterized by red, well-delineated plaques with silvery scales that are usually on the extensor surfaces and scalp. "Aryl hydrocarbon receptor (AHR)-dependent responses were also evaluated in CD69-deficient mice in a model of psoriasis induced by IL-23, as these mice developed mild psoriasis and showed reduced IL-22 and STAT3 levels." (PMID 37223078, 2023). "Total memory, central memory, effector memory, and naïve CD8 T cell subpopulations from psoriasis patients exhibited a significantly lower percentage of CD69+, Granzyme B+, and IFNγ+ cells compared to healthy controls when stimulated with anti-CD3/CD28." (PMID 40391222, 2025). "We observed reduced functionality of peripheral blood CD8 T cells from psoriasis patients compared to healthy control, with a significant decrease in CD69, Granzyme B and IFNγ expression across CD8 T cell subsets following TCR-dependent stimulation." (PMID 40391222, 2025). "CD161 serves as a marker for NK cells that can respond to IL-12 and IL-18 during differentiation, leading to the subsequent upregulation of NKp30, CD160, CD25, CD69, and IFN-γ—an identified psoriasis-associated pathogenic factor." (PMID 38596682, 2024). "Some therapies and/or procedures have been shown to impact CD69 expression in subjects with psoriasis." (PMID 37892710, 2023). "While discussing CD69 and psoriasis, this molecule has been shown to be a tissue-resident memory T cell (TRM) marker, together with CD8 and CD103." (PMID 37892710, 2023). "Our results and data from the literature support the role of the activation markers CD25 and CD69 on PBMCs in psoriasis." (PMID 37892710, 2023). "Literature data concerning the role of CD25 and CD69 in psoriasis are quite sparse and require expansion." (PMID 37892710, 2023). "In this study, we evaluated the expression of the activation markers CD25 and CD69 on peripheral blood mononuclear cells (PBMCs) in subjects with psoriasis and healthy individuals." (PMID 37892710, 2023). "While the proportion of iNKT2 and iNKT17 augmented in psoriasis patients, the CD69 expression decreased relatively." (PMID 35186952, 2021). "The frequency of peripheral iNKT cells and CD69+iNKT cells was significantly decreased in psoriasis patients." (PMID 35186952, 2021). "A higher number of CD69-positive CD4+ T cells were found in the psoriasis patients than in the healthy controls." (PMID 35186952, 2021). "The percentage of CD69+iNKT cells was reduced in the PBMCs of psoriasis patients, suggesting that iNKT cells are less activated in psoriasis patients competed to healthy controls." (PMID 35186952, 2021). "Similarly, effector CD8 T cells showed a significantly lower CD69 and IFNγ expression in psoriasis patients." (PMID 40391222, 2025). "Our results support a role for activation markers, especially CD69, in psoriasis." (PMID 37892710, 2023). "In our study, we found a decrease in the CD69+ subset in psoriasis patients." (PMID 35186952, 2021). "We found that CD69 mainly expressed in CD8αα+TEM cells in dermis of psoriasis lesions." (PMID 35663772, 2021). "Moreover, approximately 17.2% of the CD8αα+T cells expressed CD69 in the epidermis of patients with psoriasis, but approximately 38.3% of the CD8αα+T cells expressed CD69 in the dermis." (PMID 35663772, 2021). "In the case of CD8 and CD69, a statistically significant difference in their amounts was demonstrated between the epidermis and the dermis, both in the control group and in patients with psoriasis (p < 0.05)." (PMID 34769769, 2021). "Furthermore, spondylarthropathic disorders, including psoriatic arthritis have also been recently characterized by an increased frequency of circulating CD8+ CD69+ T cells compared to psoriasis and healthy controls." (PMID 32248339, 2020). "Psoriasis, a disease that can be mediated by CD8+ TRM cells co-expressing CD8 and CD69, has detectable FABP5 protein expression in skin lesions." (PMID 38596682, 2024).
psoriasis (continued). "In our work, we performed statistical analysis of CD69 and CD25 expression on different PBMCs with PASI, BSA and the duration of psoriasis, but we found only a few correlations." (PMID 37892710, 2023). "Significantly higher concentrations of CD3/CD69-, CD8/CD69- and CD19/CD69-positive PBMCs were shown in patients with psoriasis when compared to the healthy control group." (PMID 37892710, 2023). "Regarding PASI, BSA and the duration of psoriasis, we found a positive correlation between the expression of CD4/CD69 within CD4 and PASI: the more severe the psoriasis was, as assessed via PASI, the higher percentages of CD4/CD69 within CD4+ lymphocytes." (PMID 37892710, 2023). "Significantly higher levels of CD3/CD69-, CD8/CD69- and CD19/CD69-positive PBMCs as well as within CD3+ cells were present in subjects suffering from psoriasis when compared to healthy controls." (PMID 37892710, 2023). "In psoriasis, they are represented by two main types: TRM CD8+CD69+CD103+ abundant in the lesional epidermis, and TRM CD4+CD69+CD103+ located in the dermis." (PMID 35054853, 2022). "Furthermore, we show that CD69+FoxP3+ and TIGIT+FoxP3+ Treg subsets are induced by VD3-primed DCs, which are especially beneficial for the targeted suppression of pathogenic Th17 cell responses that contribute to disease progression in psoriasis and rheumatoid arthritis, among others." (PMID 35874744, 2022). "In patients with psoriasis, an increase in the CD8 and CD69, IL-17A and IL-22 immunoreactive area in the epidermis was found, but it did not change significantly in the dermis compared to the control group." (PMID 35886201, 2022). "In contrast to HCs and CD20 ̄ T cells, psoriasis patients’ CD20+T cells were enriched with CD4+T cells, displayed an activated phenotype (CD69) and secreted greater IFN-γ, TNF and IL-21 as assessed flow cytometrically." (PMID 35951029, 2022). "It has been previously reported that CD69, CD103 and CLA are highly expressed on the surface of TRM cells in the skin of patients with psoriasis." (PMID 32929360, 2020). "The frequency of CD69+, Granzyme B+ and IFNγ+ CD8 T cells in psoriasis patients was significantly lower following anti-CD3/CD28 stimulation (p<0.0005), suggesting downregulated TCR-dependent activation and impaired Tc1 cytokine production in CD8 T cells from psoriasis patients." (PMID 40391222, 2025). "In patients with psoriasis who were treated with biologic drugs, the levels of CD3/CD69-, CD4/CD69- and CD19/CD69-positive PBMCs, and CD3/CD69 within CD3+ cells, CD4/CD69 within CD4+ cells, CD4/CD25 within CD4+ cells and CD19/CD69 within CD19+ cells were significantly higher than before therapy." (PMID 37892710, 2023). "In 84 patients with psoriasis, of whom 28 were treated with different biologic drugs, as well as in 29 healthy control subjects, the expression of CD25 and CD69 on different subtypes of peripheral blood mononuclear cells (PBMCs) was studied with the use of flow cytometry." (PMID 37892710, 2023). "CD8+ TCM from PsA patients cells also display significantly higher percentage of CD69+ cells compared to CD8+ TCM from patients with psoriasis without articular involvement." (PMID 31350460, 2019). "Even more important findings demonstrated that CD69 on the skin Tγδ cells controls the secretion of IL-22 by regulating the uptake of L-tryptophan by aromatic amino acid transporter complex LAT1-CD98, which contributes to the development of psoriasis induced by IL-23." (PMID 37892710, 2023). "In addition, although we found CD103+CD8αα+TRM cells infiltrated the epidermis of psoriasis, some of them did not express CD69." (PMID 35663772, 2021). "iNKT cells anergy may also be a reason for the decrease of CD69+iNKT cell in the PBMCs of psoriasis patients, although it’s not the primary mechanism." (PMID 35186952, 2021).
psoriasis (continued). "Whilst CD69 is generally absent on CD20+T cells in HCs, in a disease model (psoriasis), there is marked up-regulation of surface CD69 indicating activation of these cells." (PMID 35951029, 2022).
leukemia (19 papers, 2009 to 2025). A malignant (clonal) hematologic disorder, involving hematopoietic stem cells and characterized by the presence of primitive or atypical myeloid or lymphoid cells in the bone marrow and the blood. "Previous studies have reported the presence of CD69+ hematopoietic stem cell (HSC)-like leukemia subpopulations across various AML subtypes, associated with poor genetic profiles and clinical outcomes." (PMID 41164126, 2025). "Nevertheless, future functional studies are needed to demonstrate the ability of CD69+ HSC-like leukemia cells to mediate chemoresistance and delineate the underlying mechanisms." (PMID 37653425, 2023). "Lower percentages of CD69+ NK cells (OR=0.32; 95% CI:0.12-0.87) and 2B4+ NK cells (OR=0.20; 95% CI:0.04-0.09) from patients older than 10-year-old were associated with higher risk of developing leukemia." (PMID 36419901, 2022). "Research has identified a drug-resistant HSC-like stem cell subpopulation characterized by the CD69 surface marker in patients with leukemia, and has preliminarily revealed that CD69 mediates drug resistance by regulating the mTOR-CCND1-CXCR4 axis." (PMID 39267837, 2024). "Different Type I IFN subtypes displayed a broad range in the capacity to induce and modulate NK cell activation and degranulation, measured by CD69 and CD107a expression in response to leukemia cell line K562." (PMID 38162640, 2023). "After cocultured with leukemia cells, the expression of activation markers CD69 and CD25 were upregulated in CAR-T cells compared with that in VEC-T cells." (PMID 34392305, 2021). "Furthermore, we explored the potential of BTK-IN-8, a novel anti-leukemia agent with CD69 inhibitory activity, which showed promising results in AML mouse models." (PMID 41164126, 2025). "CD69 may serve as a potential biomarker in defining a subpopulation of chemoresistant leukemia stem cells." (PMID 37653425, 2023). "Various surface markers, such as CD93, CD69, and CD36, have been found to demarcate distinct subpopulations of immunophenotypically sorted HSC-like cells (CD34+CD38−) that differ in leukemia initiating activity and cell cycle status." (PMID 37653425, 2023). "Collectively, this macrophage repolarization had downstream effects on T cells within the leukemia microenvironment, including decreased PD-1+Tim-3+ and LAG3+ checkpoint expression, and increased CD69+CD107a+ expression." (PMID 36960055, 2023). "The expression patterns of Tregs-associated markers (CD25, LAG-3, killer cell lectin like receptor G1, CD69, Eomesodermin - EOMES) that determines their suppressive functions was recently presented in both CLL patients and leukemia-bearing mice." (PMID 35296093, 2022). "CSPG4-CAR T cells evinced a significantly higher CD69 and CD25 upregulation compared to control CEA-CAR T cells following co-culture with KOPN8 leukemia cells, confirming antigen-specific activation mediated via CSPG4 CAR." (PMID 31195686, 2019). "Since CD69 is upregulated in proliferating T–cells in a TCR–dependent manner, these results suggest that the proliferation of those leukemia/lymphoma cells occurs independently of TCR engagement." (PMID 20011522, 2009). "Using different in vitro models of CAR123 co-culture with BPDCN and AML cell lines, we show that both TKIs reduce CAR123 activation phenotype (CD69 and CD25), tumor necrosis factor α (TNF-α) and interferon-γ (IFN-γ) secretion; degranulation (CD107a); and killing of leukemia cells." (PMID 41477551, 2025). "We confirmed that the significant decrease of leukaemia counts was mainly driven by CAR T cell activation where patient CAR T cells enhanced their surface expression of CD69 in matched leukaemia chips but not in control chips." (PMID 40595437, 2025). "Upon leukemia development in the TCL1 AT model, we observed an accumulation of antigen-experienced CD4+ T cells that show signs of activation as measured by CD69 expression." (PMID 33526861, 2021).